MRPS15 (mitochondrial ribosomal protein S15)
Synonyms: S15mt; RPMS15; DC37; FLJ11564; uS15m; MPR-S15
Tractability: Small molecule: a structure with a bound ligand is known. PROTAC: ubiquitination databases record sites on it; its protein half-life has been measured.
Gene: Protein-coding gene on chromosome 1 (36,455,718 to 36,464,418, reverse strand). Ensembl gene ENSG00000116898.
Subcellular location: Mitochondrion matrix
Subcellular location (Human Protein Atlas): Mitochondria
Pathways (Reactome):
Metabolism of proteins: Mitochondrial ribosome-associated quality control; Mitochondrial translation elongation; Mitochondrial translation initiation; Mitochondrial translation termination
Gene Ontology:
Molecular function: protein binding; RNA binding; structural constituent of ribosome
Biological process: mitochondrial translation; translation
Cellular component: mitochondrial matrix; mitochondrial small ribosomal subunit; mitochondrion; mitochondrial inner membrane; mitochondrial ribosome; ribosome
Genetic constraint (gnomAD): Loss-of-function variants: 24 observed, 29.23 expected, observed/expected ratio (o/e) 0.82, 90% interval 0.59 to 1.15. The upper end of that interval is the gene's LOEUF score, 1.15, which puts it in group 5 of 6, group 1 being the genes least tolerant of losing a copy. Missense variants: 303 observed, 321.33 expected, observed/expected ratio (o/e) 0.94, 90% interval 0.86 to 1.04. Synonymous variants: 119 observed, 120.47 expected, observed/expected ratio (o/e) 0.99, 90% interval 0.85 to 1.15.
Homologues: Orthologues: chimpanzee MRPS15 (98% identical), macaque MRPS15 (86% identical), guinea pig MRPS15 (70% identical), rabbit MRPS15 (69% identical), pig MRPS15 (66% identical), mouse Mrps15 (63% identical), rat Mrps15 (63% identical), dog MRPS15 (56% identical), tropical clawed frog mrps15 (42% identical), zebrafish mrps15 (39% identical), Drosophila melanogaster bonsai (23% identical), Caenorhabditis elegans mrps-15 (21% identical).
Diseases named in the same sentence as MRPS15 in open-access papers:
MRPS15 is named in the same sentence as 4 diseases in open-access papers, as found by Europe PMC text mining. Sharing a sentence is not in itself a finding about the gene and the disease. The quoted sentences say what the papers report.
depressive syndrome (1 paper, 2019). "Especially, MRPS15 (chromosome 1p34.3) is a clinical candidate for depressive syndrome (O’Brien, O’Brien & Norman, 2005)." (PMID 31275757, 2019).
lung fibrosis (1 paper, 2020). "ZnO specific gene signature further englobed the overexpression of Pla2g16 (FC + 7) a membrane damage sensor; S100a4 (FC + 7) involved in macrophage-induced lung fibrosis; Rps14 (FC + 6), Rps27 (FC + 5), and Mrps15 (FC + 5), three protein synthesis regulators." (PMID 31352547, 2020).
MRPS15 also shares sentences with these, for which no sentence is quoted: cancer (2 papers); tumor (1).